BCL2 (BCL2 apoptosis regulator)
Diseases named in the same sentence as BCL2 in open-access papers (continued):
Sharing a sentence is not in itself a finding about the gene and the disease.
osteosarcoma (continued). "The present study is based on the hypothesis that there is a direct correlation between the response to chemotherapy, patient survival and bcl-2 expression in human osteosarcoma." (PMID 24137369, 2013). "Inhibition of the Hedgehog pathway by ATO treatment may downregulate Bcl-2 and Bcl-xL to promote apoptotic cell death in osteosarcoma cells." (PMID 23861973, 2013). "Therefore, bcl-2 expression was significantly higher in the centrally-located high-grade osteosarcomas (P=0.0343)." (PMID 24137369, 2013). "In the present study, bcl-2 expression was analyzed in 49 osteosarcoma biopsy samples." (PMID 24137369, 2013). "However, modulation of bcl-2 expression using GO as a carrier could contribute toward innovative approaches for osteosarcoma, pending validation in tumour-relevant models." (PMID 41998059, 2026). "Interestingly, in osteosarcomas, there were reports that Bcl-2 could be modulated by miRNA expression, namely miR-143." (PMID 37720343, 2023). "In addition, our study showed that low Sestrin2 expression can effectively reduce autophagy of human osteosarcoma cells after chemotherapy, increase p-mTOR expression, decrease Bcl-2 expression, promote osteosarcoma cell apoptosis, and slow down tumour progression in NU/NU mice." (PMID 34646824, 2021). "Thus, Lnc-MAP6-1:3 may regulate the development of osteosarcoma through Bax/Bcl-2 and Wnt/β-catenin signaling pathway." (PMID 32922188, 2020). "The ethanol extract of So. lyratum Thunb could significantly produce cytotoxicity and induce apoptosis via alteration of the Bcl-2/bax ratio by downregulating the level of Bcl-2 protein while upregulating the level of Bax protein in human osteosarcoma U-2 OS cells." (PMID 31354479, 2019). "Studies have shown that icariside II could also significantly inhibit the cell growth and induce apoptosis through upregulation of Bax, cleaved caspases-3, -7, -9, and poly (ADP-ribose) polymerasein, as well as downregulation of Bcl-2 in human osteosarcoma U2OS cells." (PMID 31354479, 2019). "Moreover, JPH203 activated the mitochondria-dependent apoptotic signaling pathway by upregulating pro-apoptotic factors, such as Bad, Bax, and Bak, and the active form of caspase-9, and downregulating anti-apoptotic factors, such as Bcl-2 and Bcl-xL in human osteosarcoma Saos2 cells." (PMID 31601917, 2019). "Therefore, the aim of the present study was to investigate bcl-2 expression in high-grade osteosarcomas to generate a clear hypothesis with regard to the value of bcl-2 expression as a prognostic factor in human osteosarcoma." (PMID 24137369, 2013). "Additional investigation into the precise processes behind A. lanata's modification of Bcl2 and its effectiveness in relation to other natural chemicals may yield important information for the creation of novel anti-cancer treatments for patients with osteosarcoma." (PMID 38738026, 2024). "Knockdown of IL-13Rα2 reduced protein and mRNA levels of cyclin D1, snail, TGF-β, and BCL2, while increasing BAX expression in osteosarcoma cells." (PMID 39598436, 2024). "This suggests that osteosarcoma cells predominantly rely on MCL-1 for their survival, while BCL-xL and BCL-2 complement MCL-1 in maintaining osteosarcoma cell survival." (PMID 39497108, 2024). "In osteosarcoma cells, it has been suggested that STAT3 mediates apoptosis by inhibiting Bcl‐2 after apatinib treatment." (PMID 37502610, 2023). "MMP9 and Bcl-2 can be regulated by c-Jun and participate in CREB3-c-Jun modulated osteosarcoma progression." (PMID 37197432, 2023). "In osteosarcoma, BCA inhibited the growth of osteosarcoma cells by activating caspase 9 and caspase 3 and by increasing the ratio of Bax:Bcl-2/Bcl-XL." (PMID 37111591, 2023). "Adding to this intricate dynamic is CREB3, a member of the leucine zipper transcription factor lineage, which can intimately bind the c-Jun promoter, thereby steering osteosarcoma evolution through genes like MMP9 and Bcl-2." (PMID 38140058, 2023).
osteosarcoma (continued). "We found that cordycepin significantly reduced the protein expression levels of Bcl-2, MMP-2, and MMP-9 and induce increased the expression levels of Bax, and Cleaved PARP in osteosarcoma cells." (PMID 34953496, 2021). "Under doxorubicin treatment of U2OS and KHOS/NP osteosarcoma cells, the expression levels of cleaved PARP1, cleaved caspase 3, and BAX increased, and the expression of BCL2 decreased with the knock-down of CSNK2A1." (PMID 34359939, 2021). "When the U2OS and KHOS/NP osteosarcoma cells were treated with doxorubicin, the expression of cleaved PARP1, cleaved caspase 3, and BAX increased, and the expression of BCL2 decreased." (PMID 34359939, 2021). "We evaluated the expression of caspase-3, PARP, Bcl-2 and Bax by Western blotting to investigate apoptosis in MG-63 and MNNG/HOS human osteosarcoma cell lines and K7M2 cells after 24 h incubation with DFO or DFX." (PMID 34281233, 2021). "The Western blot results show that the iron chelators DFO and DFX promoted caspase-3 activation and significantly increased the levels of C-PARP and Bax and decreased the levels of Bcl-2 and PARP in osteosarcoma cells." (PMID 34281233, 2021). "MiRNA-143 levels were also found to be downregulated in chemo-resistant SAOS-2 and U2OS osteosarcoma cells, leading to changes in autophagic pathways, namely via ATG2B, Bcl-2, and/or LC3-II." (PMID 31979312, 2020). "A recent bioinformatic analysis of osteosarcoma miRNA signatures suggests that Bcl-2, VEGFA, CCDN1, PTEN, and Met are central driving factors in osteosarcoma." (PMID 33396725, 2020). "We found that BD treatment induced significant apoptosis in osteosarcoma cells, as detected by Annexin V/7‐AAD staining, and expression of cleaved caspase 3 and Bcl‐2." (PMID 31631559, 2019). "In osteosarcoma cells, circ-UBAP2 acts as an miR-143 sponge and suppresses apoptosis by upregulating Bcl-2." (PMID 31584877, 2019). "Overall, our results indicate that LicA significantly induced mitochondrial apoptosis in human osteosarcoma cells in vitro and in vivo, as expressed by the increase in cleaved caspase-3, -9, and PARP protein expression and Bax/Bcl-2 ratio." (PMID 31739642, 2019). "Kv1.5 was instead overexpressed in osteosarcoma and its silencing could suppress osteosarcoma progression inducing cell cycle arrest at G0/G1 phase, and apoptosis through up-regulation of p21, p27, Bax, Bcl-XL, and caspase-3 and down-regulation of cyclins A, cyclins D1, cyclins E, Bcl-2, and Bik." (PMID 30011966, 2018). "Upregulation of miR-143 was correlated with the sensitization of osteosarcoma cells to DOX, which is accompanied by downregulation of LC3-II and Bcl-2." (PMID 28978183, 2017). "In conclusion, we found that the inhibition of WWOX expression, which was due at least in part to DNA methylation, inhibited apoptosis, promoted invasion, upregulated bcl-2, OPN, RUNX2, and VEGF expression, and increased MVD in osteosarcoma cells." (PMID 28977834, 2017). "WWOX promoted apoptosis and inhibited invasion and expression of bcl-2, OPN, RUNX2, and VEGF in osteosarcoma cells in vitro." (PMID 28977834, 2017). "Here, we found that WWOX inhibited the expression of RUNX2, bcl-2, OPN, and VEGF in osteosarcoma cells." (PMID 28977834, 2017). "Treatment of various osteosarcoma cells resulted in increased cellular levels of BAX and a decreasing cellular level of Bcl-2." (PMID 28773642, 2016). "Specifically, PVT1 negatively regulated miR-195 in osteosarcoma cells, and silencing PVT1 by siRNA suppressed BCL2, CCND1, and FASN protein expression via miR-195 in osteosarcoma cells." (PMID 27813492, 2016). "First, four human osteosarcoma cell lines were treated with ABT-737, a BH3 mimetic that inhibits Bcl-w, Bcl-xL and Bcl-2; of which only Bcl-xL was identified in the siRNA screen." (PMID 26416351, 2015).
osteosarcoma (continued). "Among these we analyzed CD133, N-Myc, CCND2, E2F1 and E2F2, Bcl-2 and IAP-2, since they are overexpressed in 3AB-OS cells and many of them were found to be frequently overexpressed in tissues of osteosarcoma patients." (PMID 25174983, 2014). "However, compared with drug-resistant osteosarcoma cells, overexpression of miR-506-3p or silencing of STAT3 decreased the expression of Bcl-2 and increased the expression of Bax, which in turn led to a decrease in the Bcl-2/Bax ratio." (PMID 38420199, 2024). "Osteosarcoma cells were extremely sensitive to dual inhibition of MCL-1 and BCL-xL, as evidenced by rapid apoptosis at low concentrations, whilst combined BCL-xL and BCL-2 antagonism had minimal impact on cell viability." (PMID 39497108, 2024). "Siglec-15 has been shown to be expressed in osteosarcoma cells and may inhibit proliferation in osteosarcoma through the signal transducer and activator of transcription 3 (STAT3/Bcl-2) pathway, while inducing apoptosis and pyroptosis." (PMID 38182638, 2024). "Similarly, in osteosarcoma, tanshinone I induced apoptosis of U2OS and MG63 cells targeting the circ_0000376/miR-432-5p/Bcl-2 axis, lowering circ_0000376 and Bcl-2 and elevating miR-432-5p." (PMID 37964867, 2023). "Bcl-2 protein expression was significantly decreased by miR-342-5p, but not by miR-4270 in the three osteosarcoma cell lines." (PMID 37719019, 2023). "Similarly, in osteosarcoma, another signal of STAT3/Bcl-2 is also shown be involved in tumor proliferation, and the silencing of SIGLEC-15 induces the upregulation of apoptosis- and pyroptosis-related proteins." (PMID 36358792, 2022). "Regarding the management of osteosarcoma, preclinical studies have shown that apatinib promotes apoptosis and autophagy through VEGFR2/STAT3/BCL-2 signaling pathways in osteosarcoma cells, as well as attenuates invasion and migration through RhoA/ROCK/LIMK2 pathways." (PMID 36387068, 2022). "Moreover, we found that the expression of the antiapoptotic protein Bcl-2 was significantly decreased in U2OS and 143B osteosarcoma cells treated with both cordycepin and cisplatin compared to those treated with either drug alone." (PMID 34953496, 2021). "In osteosarcoma, apatinib exerted its antitumor effects via VEGFR2/STAT3/BCL-2 pathway." (PMID 34429133, 2021). "A higher basal expression of the anti-apoptotic Bcl-2 and Bcl-xL proteins in D-17 than in U2-OS cell line may account for lower sensitivity to Pt-TCEP of the canine osteosarcoma cell line." (PMID 32260403, 2020). "Moreover, co-treatment of siRNA for PARP1 and doxorubicin stimulated apoptotic signaling of osteosarcoma cells as indicated by an increase of cleaved PARP1 and BAX and a decrease of BCL2 expression." (PMID 29784019, 2018). "The results of this study have elucidated that FA could promote apoptosis through activated both caspase-3 and Bax and inactivated Bcl-2, and significantly descend cell viabilities in both SaOS-2 and MG63 osteosarcoma cell lines." (PMID 28367185, 2017). "Overexpression of Let-7d also reduced osteosarcoma cell sensitivity to apoptosis induced by chemotherapy agents DOX, CDDP, etoposide and paclitaxel, concomitant with a decrease in caspase-3 and increase in BCL2 expression." (PMID 28978183, 2017). "To characterize the regulatory cascade involving WWOX, bcl-2, OPN, RUNX2, and VEGF in osteosarcoma cells, we transfected MG-63 cells overexpressing WWOX with bcl-2 or RUNX2 expression plasmids and measured WWOX, bcl-2, OPN, RUNX2, and VEGF expression using Western blotting." (PMID 28977834, 2017). "Furthermore, we showed that WWOX also inhibited the expression of bcl-2, OPN, and VEGF in osteosarcoma cells." (PMID 28977834, 2017). "In addition, it is also shown that Apatinib treatment of osteosarcoma xenografts led to decreased expression of BCL-2 and increase in cleaved-PARP, and suppressed growth of osteosarcoma in vivo." (PMID 28837148, 2017).
osteosarcoma (continued). "To determine whether WWOX regulates bcl-2, RUNX2, VEGF, and OPN expression in osteosarcoma cells, we used Western blotting and qRT-PCR to examine protein and mRNA levels of these factors in U2OS, SAOS2, and MG-63 cells with WWOX overexpression or knockdown." (PMID 28977834, 2017). "Moreover, silencing PVT1 by siRNA inhibited BCL2, CCND1, and FASN protein expression via miR-195 in osteosarcoma cells, and BCL2 inhibited the si-PVT1#1-induced apoptosis of U2OS cells." (PMID 27813492, 2016). "PVT1 increased the expression levels of BCL2, CCND1 and FASN by inhibiting miR-195 in osteosarcoma." (PMID 27813492, 2016). "0.125, 0.25, 0.5, 1, 2, 4, and 8 μmol/L HYG were taken to act separately on logarithmic growth phase osteosarcoma HOS cells, CCK-8 assay was used to determine cell viability, and immunohistochemical SP assay was used to determine the expression of hTERT and Bcl-2 protein." (PMID 25371846, 2014). "The osteosarcoma patients were divided into bcl-2-positive and -negative groups and compared with regard to the response to pre-operative chemotherapy and the survival outcome." (PMID 24137369, 2013). "In patients with osteosarcoma, 21/49 cases (43%) were positive for bcl-2 expression and the remaining cases were negative." (PMID 24137369, 2013). "Despite the higher expression of bcl-2 in axial osteosarcomas, the results indicate that bcl-2 expression in high-grade osteosarcoma is not a reliable prognostic or predictive marker." (PMID 24137369, 2013). "In conclusion, the results of the present study indicate that, despite higher bcl-2 expression in central osteosarcoma, the expression in high-grade osteosarcoma is not a reliable prognostic or predictive marker." (PMID 24137369, 2013). "In addition, apatinib has been shown to inhibit osteosarcoma cell proliferation and induce osteosarcoma cell apoptosis and G0/G1 phase arrest in vitro, and inhibit cell invasion, migration and PD-1 expression, and the STAT3/ Bcl-2 signaling pathway is considered as a possible mechanism." (PMID 33892656, 2021). "Furthermore, western blot results showed that miR-29a significantly inhibited the expression of NFIA, anti-apoptosis protein Bcl-2, and EMT marker N-cadherin, but promoted the expression of pro-apoptotic protein Bax and EMT marker E-cadherin in osteosarcoma cells." (PMID 33794884, 2021). "However, although two other studies also reported high Bcl-2 staining in osteosarcoma patient samples, neither were able to correlate Bcl-2 expression with survival." (PMID 32961800, 2020). "Also in osteosarcoma cell lines a selective Bcl-2 inhibitor could not sensitize for doxorubicin, whereas WEHI-539 treatment resulted in a synergistic effect." (PMID 30242253, 2018). "While co-inhibition of BCL-2 and BCL-xL failed to induce osteosarcoma cell death, co-inhibition of MCL-1 with either BCL-2 or BCL-xL led to rapid apoptosis, underscoring the predominant role of MCL-1 in osteosarcoma cell survival." (PMID 39497108, 2024). "Conversely, when we compared potencies of the two BCL-2 inhibitors in EWS-FLI1 negative cancer cells, U2OS osteosarcoma and KBM7 chronic myeloid leukemia cell lines, we observed markedly different patterns than in EwS." (PMID 30123424, 2018). "WWOX overexpression decreased, while WWOX knockdown increased, RUNX2, bcl-2, VEGF, and OPN protein and mRNA levels in osteosarcoma cells compared to the normal and negative controls." (PMID 28977834, 2017). "However, the osteosarcoma cells tested in this study failed to respond to ABT-199, regardless of BCL-2 expression." (PMID 39497108, 2024). "Moreover, OLE and the combined treatment also obviously caused the upregulation of cleaved caspase-9 and the downregulation of Bcl-2, whereas DDP alone only slightly increased the activation of caspase-9 in 143B and U-2OS cells and did not alter the expression of Bcl-2 in any osteosarcoma cells." (PMID 30267330, 2018).
diabetes (159 papers, 2006 to 2026). "The BCL2 gene, known for its role in cell survival, is implicated in diseases like polycystic ovary syndrome, diabetes mellitus, and various cancers." (PMID 39337647, 2024). "Meanwhile, CD38 deficiency also significantly decreased the diabetes-induced increase in the Bax/Bcl2 ratio, which was an indicator of apoptosis in mice." (PMID 37958991, 2023). "Diabetes caused extensive damages in heart tissue of rats (group D) and increased expression of caspase-3 and Bax genes and enhanced ratio of Bax/Bcl-2 expression compared with controls." (PMID 35935389, 2022). "Diabetes caused a considerable decrease in the Bcl-2 gene expression of STZ-induced diabetic rats when compared to the control group (p = 0.006)." (PMID 34458667, 2021). "Rather, an increase in the association of IP3Rs with the anti-apoptotic protein Bcl-2 was suggested as a potential culprit in enhancing IP3-evoked [Ca2+]i during diabetes, as this protein is known to “sensitize” IP3Rs." (PMID 32594191, 2021). "Our results implicated diabetes exacerbated IR-induced myocardial dysfunction through downregulated BAG3/Bcl-2/Nrf-2/HO-1 expression, increased p22/p67/caspase 3/PARP/apoptosis-mediated oxidative injury and impaired microvascular reactivity." (PMID 32751309, 2020). "B-cell lymphoma 2 (Bcl-2) and Bcl-2-associated X protein (Bax) expression was measured using western blotting to further study diabetes-induced apoptosis in penile tissues." (PMID 27283992, 2016). "Diabetes caused significant reduction in the level of Bcl-2, which was again restored by naringenin (3.62-fold)." (PMID 28962270, 2014). "Interestingly, a majority of exDMP genes (about 65%), including BCL2, are associated with diabetes in the GWAS Catalog." (PMID 40637488, 2025). "In summary, the results of our present study show that overexpression of Bax and low expression of LC3 and Bcl-2 in periodontal tissues of diabetic rats may be involved in the process of periodontal tissue damage caused by diabetes." (PMID 34178461, 2021). "Thus, STZ-induced diabetes caused a significant elevation in the Bax/Bcl-2 mRNA ratio in the testis compared to NC." (PMID 33187275, 2020). "One previous report stated that diabetes increased myocardial IR injury-induced oxidative stress and impaired cardiac protection associated with the enhancement of cardiomyocyte caspase 3 activity and decrease in B-cell lymphoma 2 (Bcl-2) expression." (PMID 32751309, 2020). "In the present study, I have elucidated the role of genetics and environmental exposures in degenerative eye diseases, specifically, how aberrant expression of BCL-2 expression is associated with the pathophysiology of Down syndrome, schizophrenia and diabetes." (PMID 30857240, 2019). "Therefore, the induction of diabetes is associated with increased ratios of Bax/Bcl-2, Bax/Bcl-xL, and increased caspase-3 activity in hippocampus which shows that apoptosis is favored in hippocampal region." (PMID 18923682, 2008). "In conclusion, dysregulation of miR-146a/miR-9/NF-κB-dependent inflammatory signaling and followed by enhancement expression levels of the AβPP, BACE1, and the ratio of Bax to Bcl-2 in the hippocampus may be an underlying mechanism in diabetes-related memory impairment." (PMID 32934245, 2020). "Western blot analysis with heart extracts showed that diabetes induced higher levels of Bcl-2-associated X protein (Bax) and cleaved caspase 3 but a lower level of B-cell lymphoma-2 (Bcl-2), suggesting that increased apoptosis may be responsible for cardiac dysfunction and remodeling." (PMID 29752433, 2018).